VEGFA (vascular endothelial growth factor A)
Diseases named in the same sentence as VEGFA in open-access papers (continued):
Sharing a sentence is not in itself a finding about the gene and the disease.
tumor (continued). "The protein quantification results of VEGFA showed that the papillary cancer samples, the tumor-adjacent tissues, and the colloid goiter samples had increased expression of this protein in comparison to the normal tissues." (PMID 32824922, 2020). "Tumor cells with upregulate VEGFA indicates high‐grade malignancy and poor outcome in different types of cancer." (PMID 33362712, 2020). "Patient age, tumor grade, status of IDH mutation and expression of seven genes (SEMA3A, SEMA3D, SEMA3F, SEMA3G, ITGB3, ITGA5, and VEGFA) significantly correlated with patient OS (p < 0.05)." (PMID 33036421, 2020). "Tumor cells can induce the blood supply by secreting angiogenic factors, like VEGFA, to stimulate angiogenesis." (PMID 32944400, 2020). "In conclusion, upregulated lncRNA IRAIN repressed tumor growth of RC through inhibition of VEGFA in vivo." (PMID 32983957, 2020). "In turn, ectopic Zeb1 in tumor cells increases VEGFA production and reciprocally induces endothelial Jag1 in a paracrine manner." (PMID 33046710, 2020). "Specifically in HCC, tumors with higher transcriptomic diversity were associated with worse OS in patients treated with ICB and these tumor cells also expressed a significantly higher level of vascular endothelial growth factor A (VEGF-A)." (PMID 33117354, 2020). "This complex promotes splicing of VEGFA pre-mRNA, which signals in a paracrine manner to macrophages and ultimately results in tumour angiogenesis." (PMID 32527287, 2020). "As a latent tumor angiogenic gene, VEGFA is responsible for the induction of new blood vessels which bring oxygen and nutrients to the tumor microenvironment, playing a key role in tumor proliferation and metastasis." (PMID 32983957, 2020). "VEGFA is the best known pro-angiogenic factor and plays a crucial role during tumor vessels’ formation." (PMID 32456248, 2020). "Immune cells such as tumour-associated macrophages (TAM), MDSC, and Tregs can function to stimulate angiogenesis through secretion of VEGFA and PGE2, thus creating an endothelial barrier; and promote immunetolerance via CTL and NK cell suppression." (PMID 32121014, 2020). "A contrasting study has shown that CXCL8 secreted by tumor cells activates proangiogenic and anti-apoptotic pathways by promoting the expression of VEGFA and bcl-2 at the invasion front, which confirms the key role of CXCL8 in tumor progression." (PMID 32201645, 2020). "KDR encodes VEGFR-2, the key receptor mediating endothelial cell proliferation and sprouting, leading to angiogenesis and tumour promotion upon binding and signalling through the VEGFA pathway." (PMID 33353148, 2020). "Possibly, the hypoxic environment inside a matrigel plug or a tumor is more heterogenous than in cultured cells, rendering more SerRSWT to remain unphosphorylated and able to inhibit VEGFA expression." (PMID 33351793, 2020). "In support of this finding, expression levels of VEGFA, a potent pro-angiogenic growth factor, were substantially decreased in the tumour stroma of PyMT-cKO mice." (PMID 31324807, 2019). "For immunohistochemistry staining, the brown areas indicate positive proteins expressions of VEGFA and Ki-67 in tumor slices." (PMID 31214503, 2019). "Activated platelets release secretory factors, such as transforming growth factor-β, vascular endothelial growth factor A, and platelet-derived growth factor, promoting tumor growth and angiogenesis." (PMID 31208371, 2019). "The knockdown of EHD1 inhibited the β-adrenergic signaling pathway, which is involved in tumor angiogenesis and VEGFA regulation." (PMID 31023336, 2019). "It has been well recognized that VEGFa from tumour cells combines VEGFR2 on the membrane of neighbouring endothelial cells." (PMID 31023337, 2019). "Tumor-associated hypoxia and increased expression of oxygen-regulated HIF transcription factors are the important inducers of VEGFA and VEGFR1 overexpression." (PMID 31570733, 2019).
tumor (continued). "VEGF and it’s receptors were considered as the most important factors in tumor angiogenesis, and VEGFA among these mediates the leading role." (PMID 30755242, 2019). "For example, in mouse models of breast cancer metastasis, CCR2+ inflammatory monocytes are attracted to the metastatic microenvironment by CCL2-producing tumor cells, where they promote vascular permeability and extravasation in a VEGFA-dependent manner." (PMID 31497019, 2019). "A large body of evidence suggests that β2AR signaling activation upregulates the expression of VEGFA and promotes angiogenesis and tumor growth." (PMID 31023336, 2019). "Further, VEGFA knockdown in tumor cells results in decreased MDSC infiltration, indicating an indispensable role for VEFG in MDSC regulation." (PMID 31417498, 2019). "The results showed that MIF expression was increased dramatically in the metastasis group (p < 0.05) and VEGFA expression positively correlated with tumor grade (p < 0.05)." (PMID 31293831, 2019). "We discovered that co-incubation of anlotinib and CQ resulted in further reduction of VEGFA levels in tumor supernatant when compared with anlotinib or CQ treatment alone and further in vivo experiments demonstrated similar results." (PMID 30755242, 2019). "Tumor cells secrete pro-angiogenic factor VEGFA which binds to VEGFR2 present over surface of endothelial cells and triggers formation of new blood vessels." (PMID 30858542, 2019). "Normalization of the tumor vasculature can affect HIF1α/VEGFa feedback and reduce TC recruitment or vasculogenic mimicry (VM) formation, leading to better clinical responses in cancer patients." (PMID 31266540, 2019). "Co-administration of anlotinib and chloroquine (CQ) further reduced VEGFA level in the tumor supernatant, compared with that of anlotinib or CQ treatment alone." (PMID 30755242, 2019). "It has been reported that activation of PI3K/AKT signaling increases VEGFA expression and promotes angiogenesis in multiple tumor types." (PMID 31728130, 2019). "Vascular endothelial growth factor A (VEGF-A) has long been considered as a powerful pro-tumor factor." (PMID 31300030, 2019). "The underlying cause of the aberrant tumor vasculature is commonly the production of the hypoxia‐regulated vascular endothelial growth factor (VEGF), in particular VEGFA." (PMID 31318171, 2019). "We detected the expression of EHD1, β2AR and VEGFA in freshly frozen xenograft tumor tissue by Western blot and found that the EHD1 levels were positively correlated with β2AR and VEGFA expression." (PMID 31023336, 2019). "Collectively, these data show that the administration of SLC-0111 not only reduces the number of tumor vessels, but also reduces vascular permeability, potentially through modulation of expression and secretion of VEGFA." (PMID 31319613, 2019). "We found ten potential prognostic genes, including eight tumor suppressor and/or driver genes (VEGFA, CCND1, BAX, IL7R, SHC1, FLT1, IL7, and JAK3), as well as two chemokines (CXCL9 and CXCL10)." (PMID 31661791, 2019). "Mechanistic analysis showed that electroacupuncture inhibited tumor angiogenesis by reducing the expression of vascular endothelial growth factor A (VEGF-A), its receptor VEGF-R and neuropilin 1 (NRP-1)." (PMID 31839752, 2019). "Tumor-infiltrating immune cells, such as ILCs, are also important pro-angiogenic mediators to increase VEGFA bio-availability and signaling during the angiogenic switch." (PMID 32117199, 2019). "VEGFA inhibition yielded reduced tumor growth together with an increase in the number of tumor-infiltrating CD8+ cells." (PMID 31892230, 2019). "Since vesicles are known to be the carriers of tumor promoting factors, we ruptured harvested vesicles by repeated freeze–thaw cycles and measured VEGFA by ELISA." (PMID 30823658, 2019). "Results confirm high expression of vascular endothelial growth factor-A (VEGF-A) in tumor tissue relative to healthy-appearing kidney, in line with the angiogenic nature of ccRCC." (PMID 30881919, 2019).
tumor (continued). "Accordantly, some studies found that after blocking VEGFA, the expression of PD-L1 in tumor tissues will be upregulated in the preclinical model." (PMID 30972298, 2019). "The Sh/R-apatinib mice showed a decreased tumor volume and a lower tumor weight than the control mice, which suggested that VEGFA inhibition impaired the EHD1-induced effect on tumor growth." (PMID 31023336, 2019). "IHC staining of CD31, p-AKT (s473), CDK5RAP3 and VEGFA in xenograft tumor tissues showed that MVD in the CDK5RAP3 overexpression group was lower than in the control group." (PMID 31728130, 2019). "In implanted tumor models, the levels of tumor-secreted VEGFA are very high, compared to those in normal tissue or organs." (PMID 31501519, 2019). "We also previously reported that compressive stress can induce the upregulation of tumor progression-related microRNAs25 and epigenetically induce the expression of VEGFA, a proangiogenic factor, from CAF cells." (PMID 31428701, 2019). "These “Bcl2-rescued” NK cells undergo a functional switch from tumor-suppressive to tumor-promoting cells, since loss of STAT5 determines upregulation of the pro-angiogenic factor VEGFA, which sustains tumor growth." (PMID 31681330, 2019). "The results of IHC demonstrated that the VEGFA and Ki-67 proteins expression were downregulated (p < 0.01) in tumor tissues." (PMID 31214503, 2019). "VEGF family was considered plays a crucial role in tumor angiogenesis, and VEGFA mediates the leading role." (PMID 30755242, 2019). "Kindlin-2 also facilitates VEGFA-dependent angiogenesis and tumour progression through the mTOR pathway." (PMID 31427543, 2019). "As expected, tumor cells in Cds2iΔEC mice were more hypoxic than those in control mice and expressed much higher VEGFA compared to non-tumor cells." (PMID 31501519, 2019). "Many studies have sufficiently confirmed that restraining the expression of MMP-2, MMP-9, and VEGFA can inhibit tumor growth, metastasis and angiogenesis." (PMID 31214503, 2019). "These recruited classical monocytes release VEGFA (a major stimulator of angiogenesis) to facilitate tumor cell extravasation and lung metastasis." (PMID 31474975, 2019). "Our data clearly show that HMGA1 and FOXM1, in addition to regulating VEGFA, have a strong impact on tumor angiogenesis." (PMID 31311575, 2019). "The formation of new blood vessels in tumors is driven by hypoxic tumor cells, tumor-associated stromal cells (TASCs), and the ECM in which they are embedded, producing vascular endothelial growth factor A (VEGFA) to initiate tumor angiogenesis." (PMID 32117199, 2019). "Live imaging analysis uncovered the presence of reverse migration of the angiogenic endothelium in cds2 mutant zebrafish upon VEGFA stimulation, and endothelium regression also occurred in postnatal retina and implanted tumor models in mice." (PMID 31501519, 2019). "In contrast to this result, VEGFA expression levels were generally (8 out of 10 pair) downregulated in primary CRC tumor tissues compared with those in the matched healthy colon tissues." (PMID 31652600, 2019). "VEGFA was the most important trigger for angiogenesis, and it was the target of miR-185, which acted as a tumor suppressor in ccRCC." (PMID 31443717, 2019). "We found that the tumour samples illustrated higher expression of VEGFA (29.2 fold) than the control group." (PMID 31277414, 2019). "The main mediators of tumour angiogenesis are both the two VEGFA isoforms, that is, the soluble VEGF121 and VEGF165, although the principal signalling tyrosine kinase receptor is the VEGF receptor 2 (VEGFR‐2; FLK, KDR in humans)." (PMID 31369203, 2019). "Several miRNAs have been reported to suppress tumor growth, metastasis, and angiogenesis via inhibiting the expression of their target gene VEGFA." (PMID 31652600, 2019). "In Dong’s research group study, they demonstrated that TUG1 promotes tumour angiogenesis via up-regulating the expression level of VEGFA by sponging miR-34a." (PMID 34968230, 2019).
tumor (continued). "VEGFA gene amplifications have been described in 4 to 8% of HCCs, thereby inducing both neoangiogenesis and tumor proliferation via the induction of hepatocyte growth factor secretion by macrophages." (PMID 31783782, 2019). "The VEGFA expression level was downregulated at the T1 and T2 stages but upregulated at the T3 stage and then similarly expressed at the T4 stage tumor tissues relative to that in the matched healthy colon tissues." (PMID 31652600, 2019). "PDAC is commonly considered a hypovascularized tumor, but relevant expression of vascular endothelial growth factor A (VEGF-A) has been observed." (PMID 31395068, 2019). "Amplifications of VEGFA gene (found in 4% to 8% of HCCs) induce both neoangiogenesis and tumor proliferation owing to the recruitment and activation of macrophages, which release hepatocyte growth factor (HGF)." (PMID 31892230, 2019). "VEGFA is a well-known cytokine that can activate tumor progression by stimulating blood vessel development." (PMID 31886201, 2019). "Accumulating evidences indicated that JAK2/STAT3 are involved in tumor angiogenesis, particularly in the regulation of VEGFA." (PMID 30755242, 2019). "We also showed that mesenchymal markers (vimentin and N-cadherin) and angiogenesis marker (VEGFA) increased and epithelial markers (E-cadherin) significantly decreased in lungs of tumor bearing mice and baicalein regressed these effects in vivo and in vitro." (PMID 30949224, 2019). "In tumor models, CDS2 deficiency enhanced the level of tumor-secreted VEGFA, which in-turn trapped tumors into a VEGFA-induced vessel regression situation, leading to suppression of tumor growth." (PMID 31501519, 2019). "WNT monotherapy induced VEGFA expression in both tumor model systems, whereas increased CD31 was observed only in the MDA-MB-231 tumors." (PMID 31861131, 2019). "Such genes include DNA repair genes (BRCA1, PCNA), a regulator of oxygen homeostasis (HIF1-alpha), anti-apoptotic genes, tumor suppressors, genes of the Akt/mTOR signaling pathway and vascular endothelial growth factor A (VEGFA)." (PMID 31205871, 2019). "EPAS1 activation, ultimately, mediates the cellular response to hypoxia and regulates target genes critical for tumor progression, such as VEGFA (angiogenesis) and GLUT1 (metabolism)." (PMID 30614188, 2019). "The anti-angiogenic capability of SF was observed by CD31 staining, in which VP and SF-treated tumors had significantly less intra-tumor vasculature, as well as by downregulation of vascular endothelial growth factor A (VEGF-A) gene expression." (PMID 31582741, 2019). "Using primary cultured endothelial cells, we show that tumor-derived factor VEGFA can induce the expression of CAII in endothelial cells." (PMID 31847904, 2019). "In humans, FOXO3 harbours tumour suppressor activity as it represses processes such as VEGFA-driven tumour angiogenesis." (PMID 30842454, 2019). "The direct or indirect targeting effects exerted by miRNAs on VEGFA and CCL2 significantly reduced lung tumour angiogenesis, tumour-associated macrophages (TAMs) accumulation, tumour growth, and metastasis in mice." (PMID 30944831, 2019). "Tumor cells secrete VEGFA and metalloproteinases, which facilitate angiogenesis and digest the extracellular matrix to provide conditions for tumor migration and invasion." (PMID 31214503, 2019). "Cross-talk between tumor tissue and immune infiltrates also leads to vascular endothelial growth factor A (VEGFA)-mediated angiogenesis in an NLRC4-dependent manner, therefore driving disease progression." (PMID 30837326, 2019). "Expression levels of VEGFA were also found to be downregulated in the tumours formed in Fib-cKO glands relative to Fib-WT glands." (PMID 31324807, 2019). "We suggest that elevated kindlin-2 promotes VEGFA-dependent angiogenesis and tumour progression via the mTOR pathway." (PMID 31427543, 2019).
tumor (continued). "TAMs express vascular endothelial growth factor A in the tumor environment and facilitate extravasation of cells from the tumor thus promoting metastasis." (PMID 31507616, 2019). "VEGFA has been reported to govern vasculogenesis and angiogenesis in most of developmental, physiological and pathological processes, including tumor angiogenesis." (PMID 31501519, 2019). "Inhibition of VEGFA and Ang-2 normalizes tumor vessels and increases IFNγ+ CD8+ T cells’ extravasation and accumulation, which further enhances the antitumor effects of PD-1 inhibitors." (PMID 31835465, 2019). "In the present study, we used paired HCC and NT tissue samples to quantitatively evaluate tumor-specific changes in expression levels of VEGFA isoforms, ratios between them and correlations of these changes with clinically relevant tumor properties." (PMID 29888133, 2018). "VEGFA-dependent upregulation of E-selectin on the luminal surface of endothelium facilities adhesion of tumor cells to endothelium and subsequent extravasation." (PMID 30061895, 2018). "Micro-vessel density (MVD), as indicated by CD-31 staining, was significantly reduced by AS-IV treatment (p < 0.01), and VEGFA expression in tumor tissues was also reduced in the AS-IV treatment group (p < 0.01)." (PMID 30157903, 2018). "Several results suggested that the role of SIRT2 in tumour angiogenesis is dependent on the STAT3/VEGFA signalling pathway." (PMID 30584257, 2018). "Deletion of myeloid-derived VEGFA was shown to improve chemotherapeutic drug delivery by normalizing the tumor vasculature." (PMID 30158456, 2018). "With respect to the canine disease counterpart, higher levels of plasma VEGFA were found in more aggressive neoplasms in a survey of spontaneously occurring tumors in dogs, including OSA." (PMID 29293555, 2018). "In 1993, a monoclonal neutralizing antibody against VEGFA was reported to inhibit tumor growth in the in vivo xenograft model." (PMID 29670046, 2018). "The employment of anti-VEGFA antibody in mouse model successfully slowed the tumor development through inhibiting the tumor cell proliferation." (PMID 29409506, 2018). "The LC09 aptamer got efficient delivery of CRISPR/Cas9, leading to effective VEGFA genome editing in the tumor." (PMID 30384431, 2018). "It correlated with qPCR results showing the highest expression of HIF1A and VEGFA in the first time-points of tumor growth (4 days)." (PMID 30412628, 2018). "Vascular endothelial growth factor-A (VEGF-A) production and tumor vessel formation were found to be more significantly enriched in ALK-rearrangement NSCLC than that in epidermal growth factor receptor or Kirsten rat sarcoma viral oncogene mutated NSCLC." (PMID 29318404, 2018). "We further showed that the function of SIRT2 in tumour angiogenesis was dependent on the STAT3/VEGFA signalling pathway in CRC cells." (PMID 30584257, 2018). "These experimental data point to the potential value of miR-17-92 as a target for blocking VEGFA-stimulated tumor angiogenesis." (PMID 29617404, 2018). "Mechanistically, VEGFA is in fact the master mediator of tumour angiogenesis in different cancer types." (PMID 30584257, 2018). "Our data demonstrated that SP1-induced ZFAS1 contributed to CRC progression by upregulating VEGFA via competitively binding to miR-150-5p, which acts as a tumor suppressor by targeting VEGFA in CRC." (PMID 30250022, 2018). "In triple negative breast cancer (TNBC) ANGPTL4 and VEGFA together to heparin-binding epidermal growth factor (HB-EGF) play a pivotal role in the acquisition of tumor aggressiveness regulating tumor angiogenesis." (PMID 29389861, 2018). "Clinical and experimental data suggest that these effects occur in the context of a high VEGFA-tumor microenvironment." (PMID 29617404, 2018).